EZH2 (enhancer of zeste 2 polycomb repressive complex 2 subunit)
Diseases named in the same sentence as EZH2 in open-access papers (continued):
Sharing a sentence is not in itself a finding about the gene and the disease.
gastric cancer (continued). "For example, lncRNA PCAT-1, which is significantly expressed in tissues and cells of gastric cancer resistant to DDP, increases DDP resistance in gastric cancer cells by engaging EZH2 to epigenetically repress PTEN expression and controlling the miR-128/ZEB1 axis." (PMID 38162289, 2023). "MALAT1 may associate with EZH2, a subunit catalyzing the trimethylation modification in histone 3 Lys27 (H3K27me3), to inhibit the expression of tumor suppressor PCH10 and increase migration and invasion in gastric cancer (GC) cells." (PMID 36452326, 2022). "In gastric cancer, EZH2 along with the histone demethylase LSD1 and DNMT1 were recruit by the lncRNA HOXA11-AS, this lncRNA also acts as sponge for miR-1297, antagonizing its ability to repress EZH2 protein translation." (PMID 36533073, 2022). "In gastric cancer (GC), ZFAS1 plays an oncogenic role by interacting with EZH2." (PMID 34249125, 2021). "EZH2 inhibition may also be a feasible treatment in gastric cancer, where ARID1A mutant tumors often have high levels of EZH2." (PMID 34691767, 2021). "CircGSK3B directly binds to EZH2 and inhibits the binding of EZH2 and H3K27me3 to the RORA promoter, leading to elevated RORA expression and inhibiting tumor progression by suppressing the growth, invasion, and metastasis of gastric cancer cells." (PMID 35116058, 2021). "This study demonstrated the efficacy of molecular hydrogen in inhibiting the growth of gastric cancer by reducing the proliferation and migration of gastric cancer cells, which was through downregulating lncRNA MALAT1 and polycomb-group family member EZH2 and upregulating miR-124-3p." (PMID 33482814, 2021). "Tumor suppressor miR-195-5p, miR-204, miR-623, miR-939 and miR-124 have been shown to be involved in overcoming 5-FU resistance of gastric cancer via silencing Zing finger 139 (ZNF139), TGFBR2, cyclin D1 (CCND1), solute carrier family 34 member 2 (SLC34A2) and EZH2, respectively." (PMID 32192494, 2020). "In addition, increased expression of this lncRNA in gastric cancer patients can predict poor prognosis and promotes tumorigenesis by epigenetically silencing EphB3 (EPH receptor B3) via EZH2 and LSD1, also known as KDM1A (lysine demethylase 1A)." (PMID 32760219, 2020). "Similarly, HOXA11-AS is able to recruit EZH2 via the DNMT1 methyltransferase complex to regulate miR-1297 and promote gastric cancer cell proliferation and invasion." (PMID 31757938, 2019). "Interestingly, this lncRNA promotes gastric cancer cell proliferation by downregulating mRNA levels of CDKN1A in vitro and in vivo via binding with enhancer of zeste homolog 2 (EZH2)." (PMID 31514410, 2019). "For the detection of the correlation between EZH2- and EMT-related proteins in human gastric cancer, we did mRNA sequencing in EZH2 knockdown cells and then analyzed the gene set enrichment for EMT, which showed a good evidence for EZH2’s regulation on EMT at the molecular level." (PMID 29335012, 2018). "Similarly, overexpression of UCA1 induced by SP1 was reported to promote cell proliferation via recruiting EZH2 and activating AKT pathway in gastric cancer." (PMID 29719612, 2018). "The expression of Ezh2 was higher in gastric cancer tissues in comparison with para-nontumorous epithelium." (PMID 29335012, 2018). "Interestingly, it was recently reported that STAT3 can bind to the promoter region of the EZH2 gene in gastric cancer cells, implicating STAT3 as direct regulator of EZH2." (PMID 29728695, 2018). "Furthermore, AGAP2-AS1 epigenetically suppresses P21 and E-cadherin expression by interacting with EZH2 and LSD1, indicating that AGAP2-AS1 also has oncogenic roles in gastric cancer." (PMID 29721215, 2018). "In this study, we also found that KLF2 can function as tumor suppressor and its' expression could be suppressed by ZFAS1 through recruiting EZH2 and LSD1 to its promoter region in gastric cancer cells." (PMID 27246976, 2017).
gastric cancer (continued). "Similarly, lncRNA LINC00152 and lncRNA CCAT2 interact with EZH2 and guides it to suppress gene expression of p15 and p21 and E-cadherin and LATS2 in gastric cancer cells to promote cancer proliferation in vitro and in vivo." (PMID 28561778, 2017). "Moreover, DUXAP8 was also found to be over-expressed in human gastric cancer, and increased DUXAP8 promoted cells proliferation and invasion through epigenetically silencing PLEKHO1 expression by binding with EZH2 and SUZ12 in gastric cancer cells." (PMID 29152119, 2017). "In the stratified analysis, no significant risks were found among gastric cancer (HR = 0.66, 95% CI: 0.16–1.15) and colorectal cancer (HR = 0.91, 0.63–1.19), indicating that EZH2 was not an indicator of poor prognosis in gastric cancer or colorectal cancer." (PMID 26859127, 2016). "Enhancer of zeste homolog 2 (EZH2) activates Ras and p65/RelA (a measure of NF-κB activity), and high EZH2 expression has been correlated with poor prognosis in several tumors, including gastric cancer." (PMID 21951562, 2011). "In gastric cancer (GC), upregulation of FOXD2-AS1 promotes carcinogenesis by epigenetically silencing EPHB3 via recruiting EZH2 and LSD1, leading to H3K27 methylation and H3K4 demethylation, respectively." (PMID 34461912, 2021). "Moreover, previous studies have found that miRNA-101 inhibits the cell proliferation and augmented apoptosis in gastric cancer, colon cancer and NSCLC by targeting zinc finger E-box binding homeobox 1 (ZEB1), cyclooxygenase-2 (Cox-2), enhancer of zeste homologue 2 (EZH2) and Mcl-1." (PMID 32212793, 2020). "Moreover, the expression data in gastric cancer tissue samples from TCGA database also reveal a significant negative correlation between Ezh2 and PTEN mRNA in human gastric cancer samples." (PMID 29335012, 2018). "However, whether Ezh2 promotes tumor cell EMT and enhances the stem cell-like phenotype via AKT/PTEN signaling pathway in gastric cancer warrants validation." (PMID 29335012, 2018). "Additionally, Sun39et al. investigated the potential mechanism of HOXA11-AS in gastric cancer cells, and they found that HOXA11-AS could play an oncogenic role through the EZH2/HOXA11-AS/LSD1 complex or HOXA11-AS/miR-1297/EZH2 crosstalk." (PMID 28717185, 2017). "In human gastric cancer, EZH2 promotes the activation of Wnt/β-catenin signaling by down-regulating CXXC4 expression, and several other Wnt pathway antagonists, including NKD1, PRICKLE1, PPP2R2B, AXIN2 and SFRP5, were concordantly silenced by EZH2 in hepatocellular carcinomas." (PMID 27926488, 2017). "Interestingly, we found that ZFAS1 could directly bind with EZH2, LSD1 and CoREST (histone demethyltransferase of REST complex) in gastric cancer cells, which suggesting that ZFAS1 might also could regulate underlying targets at transcriptional levels." (PMID 27246976, 2017). "However, the combined HRs of gastric cancer and colorectal cancer were (HR = 0.66, 95% CI: 0.16–1.15) and (HR = 0.91, 95% CI: 0.63–1.19), respectively, indicating EZH2 was not an indicator of poor prognosis in gastric cancer or colorectal cancer." (PMID 26859127, 2016). "In a previous meta-analysis that included four Asian studies, it was observed that the OS of EZH2-negative patients was shorter than that of patients with positive expression for gastric cancer (HR = 0.54, 95% CI: 0.05–1.03), which was similar to our finding (HR = 0.88, 95% CI: 0.23–3.34)." (PMID 25974088, 2015). "MNX1-AS1 activated by TEAD4 can promote the GC process through EZH2/BTG2 and miR-6785-5p/BCL2 axes, suggesting that it was a novel and effective therapeutic target for gastric cancer." (PMID 34712264, 2021).
hepatocellular carcinoma (240 papers, 2005 to 2026). A malignant tumor that arises from hepatocytes. "Enhancer of zeste homolog 2 (EZH2), a key protein implicated in various cancers including hepatocellular carcinoma (HCC), is recognized for its association with epigenetic dysregulation and pathogenesis." (PMID 39516467, 2024). "It is clearly confirmed that the G553C point mutation of EZH2 in hepatocellular carcinoma is a significant protective genetic change." (PMID 38764053, 2024). "Previous reports on hepatocellular carcinoma indicated an association between the transcription factors EZH2 and B-Myb." (PMID 37443739, 2023). "EZH2 overexpression levels were associated with poor prognosis of cancer, especially hepatocellular carcinoma." (PMID 35659256, 2022). "Increased levels of Ezh2 and H3K27me3 are found in hepatocellular carcinoma (HCC) and are associated with metastasis and poor prognosis." (PMID 32428001, 2020). "CAFs have been reported to promote angiogenesis via VEGF secretion in hepatocellular carcinoma, which is associated with up-regulation of enhancer of zeste homolog 2 (EZH2) and further inhibition of vasohibin 1 (VASH1)." (PMID 32957712, 2020). "However, the function of EZH2 splice variants as well as the mechanism by which EZH2 alternative splicing occurs in hepatocellular carcinoma (HCC) remain elusive." (PMID 39850359, 2025). "However, in hepatocellular carcinoma cells, EZH2 enhances H3K27me3 at the promoters of CD274, which encodes PD-L1, and interferon regulatory factor 1 (IRF1), leading to an inverse correlation by inhibiting PD-L1 expression." (PMID 40308579, 2025). "The authors proposed that EZH2 suppresses PD-L1 expression via epigenetic modification, by upregulating H3K27me3 levels at the CD274 (which encodes PD-L1) and IRF1 gene in hepatoma cells, highlighting the critical role of EZH2 in reshaping the tumour immune microenvironment." (PMID 40310411, 2025). "For instance, we observed upregulation of EZH2 in liver cancer samples with a mutation in the predicted distal enhancers of the EZH2 gene, which is known to promote hepatocellular carcinoma (HCC) progression and metastasis and its inhibitors are currently being tested in clinical trials." (PMID 36625266, 2023). "Notably, a recent study suggested that enhancer of zeste homolog 2 (EZH2) can suppress PD-L1 expression by directly upregulating H3K27me3 levels at CD274 (encoding PD-L1) promoter regions in hepatoma cells." (PMID 33324209, 2020). "In addition, miR-101 played an vital role in EZH2-induced sorafenib resistance and cancer-associated fibroblasts in hepatocellular carcinoma." (PMID 33324633, 2020). "However, some research has indicated that the EZH2-mediated loss of miR-622 determines CXCR4 activation in hepatocellular carcinoma." (PMID 32635336, 2020). "Moreover, re-expression of IRF1 also partly rescued the reduced luciferase activity of P1 caused by knockdown of IRF1 in the EZH2-silenced hepatoma cells." (PMID 31727135, 2019). "One of the lncRNAs, lncRNA-HEIH (hepatocellular carcinoma upregulated EZH2-associated lncRNA), inhibits the expression of cell cycle regulatory genes via histone methylation mediated by enhancer of zeste homolog 2 (EZH2), a component of the PRC2 complex, and facilitates cell growth." (PMID 38297160, 2024). "The overexpression or knockdown of miR-506-3p or EZH2 was tested to see if it might reverse the liver tumor development caused by circSYPL1 in order to better identify the biological role of these three molecules in the development of hepatocellular carcinoma." (PMID 35345511, 2022). "Furthermore, EZH2 has been identified to be a promising tumor biomarker, and it represents a prognostic biomarker associated with immunosuppression in esophageal squamous carcinoma and hepatocellular carcinoma." (PMID 34790699, 2021).
hepatocellular carcinoma (continued). "Likely in hepatocellular carcinoma, specific lncRNAs recruit polycomb proteins (EZH2, SUZ12) and histone demethylases (KDM2A) to FGFR2 loci, facilitating exon IIIb inclusion and favoring tumor-suppressive isoform expression." (PMID 41584352, 2026). "EZH2 is highly expressed in hepatocellular carcinoma (HCC) and can regulate the levels of histone H3K27me3 in the promoter region of TFR2, maintaining iron homeostasis in HCC and inhibiting ferroptosis." (PMID 40299567, 2025). "Another important lncRNA associated with HBV-related HCC is High Expression in Hepatocellular Carcinoma (HEIH), which was reported to promote liver cancer and regulates the cell cycle via miR-129→ EZH2 in HepG2.2.7.1 cells." (PMID 40625740, 2025). "At the same time, activation of SIRT7 super enhancer was found in all samples in hepatocellular carcinoma, and it was found that SIRT7 and methyltransferase EZH2 were co expressed and bound in hepatocellular carcinoma." (PMID 39838405, 2025). "Sorafenib, a first-line therapeutic agent for the treatment of hepatocellular carcinoma, increases H3K27me3 levels in tumor cells and induces EZH2 activation after long-term treatment." (PMID 40042761, 2025). "Using data from the TCGA-LIHC cohort accessed via the UALCAN platform, both mRNA and protein expression levels of EZH2 were found to be significantly elevated in hepatocellular carcinoma (HCC) tissues compared to normal liver tissues." (PMID 41209556, 2025). "For instance, the miR-144/miR-451a cluster, silenced by EZH2, promotes M1 polarization of TAMs, enhancing anti-tumor immunity in hepatocellular carcinoma." (PMID 38534385, 2024). "Enhancer of zeste 2 polycomb repressive complex 2 subunit (EZH2) is overexpressed in hepatocellular carcinoma, promoting tumorigenesis and correlating with poor prognosis." (PMID 39640777, 2024). "For example, TRIM25 activates NRF2 and promotes the progression of hepatocellular carcinoma, regulates the stability of EZH2, thereby promoting the resistance of colorectal cancer to oxaliplatin." (PMID 38926803, 2024). "EZH2 silences Wnt pathway antagonists, activating Wnt/β-catenin signalling in hepatocellular carcinomas, contributing to their proliferation and suggesting a potential therapeutic target." (PMID 39236081, 2024). "In hepatocellular carcinoma cell lines, EZH2, the histone methyltransferase subunit of the polycomb repressor complex, binds to PRICKLE1 promoter and suppresses its expression." (PMID 39314474, 2024). "Later studies with more specific EZH2 inhibitors showed that in hepatocellular carcinoma the combination of 5-azadeoxycitidine with the EZH2 inhibitor GSK126 increased expression of neoantigens, increased tumor-infiltrating lymphocytes and reduced cell growth." (PMID 37664059, 2023). "EZH2 has been shown to suppress the expression of p27 in hepatocellular carcinoma cells through methylation of the p27 promoter." (PMID 38264522, 2023). "In hepatocellular carcinoma associated with non-alcoholic fatty liver disease, YTHDF1 can directly target EZH2 mRNA to promote EZH2 translation, leading to the production of cytokine IL-6 in tumor cells." (PMID 38202722, 2023). "EZH2 knockdown by siRNA in hepatoma cells increased the sensitivity to sorafenib and thus decreased the viability of tumor cells." (PMID 37268997, 2023). "EZH2 inhibition enhances the eradication of hepatocellular carcinoma by NK cells in hepatocellular carcinoma." (PMID 37909018, 2023). "Lately, EZH2 independent effects of SAM-competitive EZH2 inhibitors have been shown in hepatocellular carcinoma cell lines and correlated with an induction of expression of the transcription factor SRE binding protein." (PMID 37297005, 2023). "Among them, miRNA-98 suppresses EZH2 expression to inhibit Wnt signaling, resulting in a decrease in hepatocellular carcinoma proliferation." (PMID 35236381, 2022).
hepatocellular carcinoma (continued). "For example, in hepatocellular carcinoma, miR-144/miR-451a is silenced by EZH2 and promotes M1 polarization, enhancing anti-tumor immunity." (PMID 36135315, 2022). "In hepatocellular carcinoma, miRNA-26a stimulates cell growth inhibition via inhibiting EZH2 expression." (PMID 35236381, 2022). "Eventually, the LINC01348/SF3B3/EZH2/JNK/c-Jun/Snail pathway inhibits hepatocellular carcinoma progression." (PMID 34750493, 2022). "Based on the EZH2 expression, the differentially expressed lncRNAs DElncRNAs), miRNAs (DEmiRNAs), and mRNAs (DEmRNAs) were identified in hepatocellular carcinoma by using the TCGA database." (PMID 36038907, 2022). "The EZH2 expression level is a different indistinct immune subtype of hepatocellular carcinoma, and C1 (wound healing) and C2 (IFN-γ) exhibited the highest expression in relation to the remaining four subtypes." (PMID 35659256, 2022). "Background and objectives: EZH2 is overexpressed in hepatocellular carcinoma (HCC) and is correlated with poor prognosis." (PMID 35208478, 2022). "According to these results, EZH2 has a critical function within the immune microenvironment and deserves to be regarded as a prognostic marker and immunotherapeutic target for hepatocellular carcinoma." (PMID 35659256, 2022). "Previous studies had reported EZH2 was related to the progression, invasion, and metastasis of the hepatocellular carcinoma." (PMID 35855852, 2022). "In this study, we aimed to analyze the clinical and prognostic values of EZH2 expression in hepatocellular carcinomas using the Total Cancer Genome Atlas (TCGA) data." (PMID 35208478, 2022). "The GEPIA database demonstrated that the expression level of EZH2 in hepatocellular carcinoma samples increased in relation to healthy controls." (PMID 35659256, 2022). "From the mechanisms that converge on EZH2 in cisplatin resistance, upregulation of miR-138 was shown to enhance sensitivity to cisplatin in hepatocellular carcinoma via regulation of EZH2." (PMID 36230683, 2022). "In hepatocellular carcinoma, miRNA-137 inhibits migration and metastasis via targeting EZH2/STAT3 signaling." (PMID 35236381, 2022). "EZH2 plays an essential role in the immune microenvironment and is a potential prognostic marker and immunotherapy target for hepatocellular carcinoma." (PMID 35659256, 2022). "Recently, UPK1A-AS1 was revealed to play an oncogenic role in hepatocellular carcinoma and protect tumor cells against cisplatin toxicity by mediating the nuclear translocation of EZH2 and competing with miR-138-5p endogenously." (PMID 35264742, 2022). "Several studies pointed out that EZH2 is significantly (P < 0.05) expressed in human hepatocellular carcinoma tissues and cell lines." (PMID 35321452, 2022). "Overall, these studies agree with the fact that miRNA/EZH2 axis can affect proliferation, metastasis, and therapy response of hepatocellular carcinoma cells, and in this way, different molecular pathways such as Wnt, STAT3 and EMT are affected." (PMID 35236381, 2022). "CircSYPL1 expression is upregulated in patients with hepatocellular carcinoma; circSYPL1 sponges miR-506-3p to elevate EZH2 expression and induce tumorigenesis in hepatocellular carcinoma cells." (PMID 35884948, 2022). "It was previously found that the expression of SOCS3 in hepatocellular carcinoma tissues and cell lines was negatively correlated with EZH2 and depended on its promoter methylation status through TCGA hepatocellular carcinoma data analysis." (PMID 34868904, 2021). "LINC00152 has been described to repress gene expression by interacting with EZH2 as well as to activate the transcription of EpCAM by binding to its promoter, thereby favoring cell proliferation in hepatoma cells." (PMID 34206504, 2021). "Alternatively, EZH2 inhibition was also reported to induce the expression of NKG2D ligands in hepatocellular carcinoma cells." (PMID 34737746, 2021).